PKD1 (polycystin 1, transient receptor potential channel interacting)
Description:
Component of a heteromeric calcium-permeable ion channel formed by PKD1 and PKD2 that is activated by interaction between PKD1 and a Wnt family member, such as WNT3A and WNT9B. Both PKD1 and PKD2 are required for channel activity. Involved in renal tubulogenesis. Involved in fluid-flow mechanosensation by the primary cilium in renal epithelium (By similarity). Acts as a regulator of cilium length, together with PKD2 (By similarity). The dynamic control of cilium length is essential in the regulation of mechanotransductive signaling (By similarity). The cilium length response creates a negative feedback loop whereby fluid shear-mediated deflection of the primary cilium, which decreases intracellular cAMP, leads to cilium shortening and thus decreases flow-induced signaling (By similarity). May be an ion-channel regulator. Involved in adhesive protein-protein and protein-carbohydrate interactions. Likely to be involved with polycystin-1-interacting protein 1 in the detection, sequestration and exocytosis of senescent mitochondria. [Isoform 4]: Plays a role in mitochondrial dynamics. In immortalized renal cyst cells, converts fragmented mitochondria to a filamentous shape.
Synonyms: PC1; PBP; Pc-1; TRPP1; eliosin
Tractability: Small molecule: a high-quality ligand is known. Antibody: UniProt places it where antibodies can reach, with high confidence; its Gene Ontology location is reachable by antibodies, with high confidence; UniProt predicts a signal peptide or a membrane-spanning region. PROTAC: a small molecule that binds it is known.
Target class: Voltage-gated ion channel; Ion channel; Transient receptor potential channel
Gene: Protein-coding gene on chromosome 16 (2,088,708 to 2,135,898, reverse strand). Ensembl gene ENSG00000008710.
Subcellular location: Cell membrane; Cell projection, cilium; Endoplasmic reticulum; Golgi apparatus; Vesicle; Secreted, extracellular exosome; Note=Component of endoplasmic reticulum-mitochondrion membrane contact sites (Isoform 4)
Pathways (Reactome):
Organelle biogenesis and maintenance: VxPx cargo-targeting to cilium
Gene Ontology:
Molecular function: calcium channel activity; protein binding; protein domain specific binding; protein kinase binding; transmembrane transporter binding; Wnt receptor activity; monoatomic cation channel activity; transcription regulator inhibitor activity
Biological process: branching morphogenesis of an epithelial tube; calcium ion transport; cartilage development; cell surface receptor signaling pathway; digestive tract development; genitalia development; heart development; lung epithelium development; mesonephric duct development; mesonephric tubule development; metanephric ascending thin limb development; metanephric collecting duct development; metanephric distal tubule morphogenesis; metanephric proximal tubule development; mitocytosis; neural tube development; positive regulation of transcription by RNA polymerase II; protein heterotetramerization; regulation of G1/S transition of mitotic cell cycle; regulation of proteasomal protein catabolic process; skin development; spinal cord development; Wnt signaling pathway; anatomical structure morphogenesis; calcium ion transmembrane transport; and 17 more
Cellular component: basolateral plasma membrane; calcium channel complex; cation channel complex; cilium; extracellular exosome; membrane; migrasome; plasma membrane; polycystin complex; vesicle; ciliary membrane; cytoplasm; endoplasmic reticulum; Golgi apparatus; Golgi membrane; Golgi-associated vesicle membrane; motile cilium; nucleus; cell surface; extracellular region; lateral plasma membrane; protein-containing complex
Genetic constraint (gnomAD): Loss-of-function variants: 74 observed, 246.95 expected, observed/expected ratio (o/e) 0.3, 90% interval 0.25 to 0.36. The synonymous counts are far from expectation, so gnomAD's model fits this gene poorly and the ratio says little. Missense variants: 5,932 observed, 4,851.2 expected, observed/expected ratio (o/e) 1.22, 90% interval 1.2 to 1.25. Synonymous variants: 3,352 observed, 2,264.7 expected, observed/expected ratio (o/e) 1.48, 90% interval 1.44 to 1.52.
Gene-disease validity (ClinGen):
ClinGen rates the evidence that PKD1 causes each of these diseases.
autosomal dominant polycystic kidney disease (autosomal dominant): Definitive. Autosomal dominant form of polycystic kidney disease.
autosomal recessive polycystic kidney disease (autosomal recessive): Definitive. An inherited disorder characterized by the development of cysts affecting the collecting ducts.
Homologues: Orthologues: macaque PKD1 (95% identical), pig PKD1 (82% identical), guinea pig PKD1 (80% identical), rat Pkd1 (79% identical), mouse Pkd1 (78% identical), tropical clawed frog pkd1 (48% identical), zebrafish pkd1a (39% identical), Drosophila melanogaster Pkd2 (3% identical), Caenorhabditis elegans pkd-2 (2% identical). Paralogues in human: PKD1L2 (11% identical), PKD1L1 (10% identical), PKDREJ (10% identical), PKD1L3 (7% identical), LOXHD1 (6% identical), DENND5B (5% identical), DENND5A (5% identical), PKD2 (4% identical), PKD2L1 (3% identical), PKD2L2 (2% identical).
Diseases named in the same sentence as PKD1 in open-access papers:
PKD1 is named in the same sentence as 249 diseases in open-access papers, as found by Europe PMC text mining. Sharing a sentence is not in itself a finding about the gene and the disease. The quoted sentences say what the papers report.
autosomal dominant polycystic kidney disease (360 papers, 2006 to 2026). "Autosomal dominant polycystic kidney disease (ADPKD) is a common inherited disorder caused by mutations in PKD1 or PKD2." (PMID 41501598, 2026). "Genetic risk stratification in autosomal dominant polycystic kidney disease relies primarily on identification of pathogenic variants in PKD1 and PKD2, which account for the vast majority of cases." (PMID 41597516, 2026). "Autosomal dominant polycystic kidney disease (ADPKD) is caused primarily by pathogenic variants in the PKD1 and PKD2 genes." (PMID 39883360, 2025). "Ultrarare damaging variants in PKD1, a gene causing autosomal dominant polycystic kidney disease, and SMAD2, a gene causing Loeys-Dietz syndrome, were associated with IA in the general population, even in the absence of a diagnosis of these disorders." (PMID 40172005, 2025). "Germline pathogenic mutations in PKD1 are known to cause autosomal dominant polycystic kidney disease (ADPKD), a condition that increases the risk of developing ESKD over time." (PMID 40770708, 2025). "The human PKD1 gene locus region is the site that when mutated, causes 87% of the cases of human autosomal dominant polycystic kidney disease (ADPKD)." (PMID 41166294, 2025). "Autosomal dominant polycystic kidney disease (ADPKD) is an inherited renal disorder that is caused by PKD1 or PKD2 mutations, affects approximately 1 in 1000 live births, and is characterised by the relentless development of renal cysts." (PMID 39747793, 2025). "TSC2/PKD1 contiguous gene syndrome is caused by deletions involving the TSC2 and PKD1 genes that lead to tuberous sclerosis complex and autosomal dominant polycystic kidney disease." (PMID 39323690, 2024). "Autosomal dominant polycystic kidney disease (ADPKD) is the most common inherited cystic kidney disease (common causative mutations involve the PKD1 and PKD2 genes) primarily affecting adults." (PMID 39125479, 2024). "Autosomal dominant polycystic kidney disease (ADPKD) occurs when the proteins Polycystin-1 (PC1, PKD1) and Polycystin-2 (PC2, PKD2) contain mutations." (PMID 38607049, 2024). "Autosomal dominant polycystic kidney disease (ADPKD) is a dominant genetic disorder caused primarily by mutations in the PKD1 gene, resulting in the formation of numerous cysts and eventually kidney failure." (PMID 39883350, 2024). "Autosomal dominant polycystic kidney disease (ADPKD) is a hereditary kidney disorder caused by mutations in the PKD1 or PKD2 genes encoding polycystin 1 (PC1) or PC2 and is characterized by the growth of excessive cysts in the kidneys." (PMID 39203885, 2024). "Autosomal dominant polycystic kidney disease (ADPKD) results from mutations in the PKD1 or PKD2 genes and affects between 1:400–1:1000 individuals worldwide, making it the leading, life-threatening monogenic illness." (PMID 39314240, 2024). "In adults, PKD1 gene mutation almost always signifies its subtype, autosomal dominant polycystic kidney disease (ADPKD), or adult polycystic kidney disease." (PMID 37554616, 2023). "The gene most commonly mutated in autosomal dominant polycystic kidney disease, PKD1, encodes a putative membrane protein with an ~3000 amino acid N-terminus, 11 transmembrane spanning (TM) domains, and an ~200 amino acid C-terminus." (PMID 37540694, 2023). "Mutations in polycystin-1 which is encoded by the PKD1 gene are the main causes for the development of autosomal dominant polycystic kidney disease." (PMID 37206967, 2023). "Autosomal dominant polycystic kidney disease (ADPKD) is a hereditary kidney disorder mostly caused by mutations in PKD1 or PKD2 genes." (PMID 37152951, 2023). "Autosomal dominant polycystic kidney disease (ADPKD) is a common monogenic multisystem disease caused primarily by mutations in the PKD1 gene or PKD2 gene." (PMID 37468838, 2023). "Inactivating mutations of the PKD1 gene are responsible for different forms of autosomal dominant polycystic kidney disease." (PMID 38093359, 2023).
autosomal dominant polycystic kidney disease (continued). "Evidence supporting PC-1 and PC-2 interdependency includes that mutations in either Pkd1 or Pkd2 result in autosomal dominant polycystic kidney disease (ADPKD), the most prevalent monogenic disorder in humans." (PMID 35229718, 2022). "Mutations in polycystin-1 encoding gene PKD1 or polycystin-2 encoding gene PKD2 were commonly seen in cases of Caroli disease associated with autosomal dominant polycystic kidney disease (ADPKD)." (PMID 35741793, 2022). "Ninety-five percent of patients with autosomal-dominant polycystic kidney disease (ADPKD) exhibit mutations in PKD1 (about 85%) and PKD2 (about 15%)." (PMID 35051185, 2022). "On the contrary, almost all ADPKD patients harbor gene mutations in polycystic kidney disease 1 (PKD1) or polycystic kidney disease 2 (PKD2)." (PMID 35806376, 2022). "Mutations in the genes Polycystic kidney disease 1 (PKD1) and Polycystic kidney disease 2 (PKD2) cause ADPKD." (PMID 36307508, 2022). "For example, cystogenesis is more extensive in mice with KO of both Nedd9 and polycystin 1 transient receptor potential channel interacting (Pkd1), a causative gene for autosomal dominant polycystic kidney disease, than in mice with KO of Pkd1 alone." (PMID 34944109, 2021). "Autosomal dominant polycystic kidney disease (ADPKD) is associated with mutations in PKD1 and PKD2, changes in apical actin and cilia dysfunction." (PMID 34250905, 2021). "Autosomal dominant polycystic kidney disease (ADPKD) is caused by germline mutations of PKD1 or PKD2 on one allele and a somatic mutation inactivating the remaining normal allele." (PMID 34315885, 2021). "Several recent studies reported that autosomal dominant polycystic kidney disease (ADPKD) is mainly caused by mutations in the PKD1 and PKD2 genes and rarely by mutations in the GANAB gene." (PMID 32550232, 2020). "PKD1 is involved in testis development and is known to cause low sperm quality in men with autosomal dominant polycystic kidney disease." (PMID 32456687, 2020). "Autosomal dominant polycystic kidney disease (ADPKD) patients with PKD1 mutations, particularly those with truncating mutations, show poor prognosis." (PMID 31948117, 2020). "Most human families with ADPKD have novel variants and over 1,273 causal variants for PKD1 are catalogued in the Autosomal Dominant Polycystic Kidney Disease Mutation Database: PKDB." (PMID 31299928, 2019). "The main mutational genes causing autosomal dominant polycystic kidney disease (ADPKD) are PKD1 and PKD2 as well as some rare pathogenic genes." (PMID 31056860, 2019). "Autosomal dominant polycystic kidney disease (ADPKD) is mainly caused by mutations in the PKD1 (~85%) or PKD2 (~15%) gene which, respectively, encode polycystin-1 (PC1) and polycystin-2 (PC2)." (PMID 31341901, 2019). "Autosomal dominant polycystic kidney disease (ADPKD) caused by PKD1 mutations is one of the most common hereditary disorders." (PMID 31822676, 2019). "Autosomal Dominant Polycystic Kidney Disease (ADPKD) typically results from a mutation in the PKD1 and PKD2 genes, which code for polycystin-1 (PC1) and polycystin-2 (PC2), respectively." (PMID 30792735, 2019). "Autosomal dominant polycystic kidney disease (ADPKD) is caused by mutations in PKD1 or PKD2 gene, encoding the polycystic kidney disease protein polycystin‐1 and the transient receptor potential channel polycystin‐2 (also known as TRPP2), respectively." (PMID 31441214, 2019). "Autosomal Dominant Polycystic Kidney Disease (ADPKD) is caused by mutation of PKD1 or PKD2, which encode polycystin 1 and 2, respectively." (PMID 29563577, 2018). "We discovered a novel pathogenic mutation in the PKD1 gene, and its underlying aetiology in a family with autosomal dominant polycystic kidney disease." (PMID 30424739, 2018).
autosomal dominant polycystic kidney disease (continued). "Mutations either on the PC1-encoding gene polycystic kidney disease 1 (PKD1) or the PC2-encoding gene polycystic kidney disease 2 (PKD2) cause autosomal dominant polycystic kidney disease (ADPKD), which represents the most common genetic disease." (PMID 30597875, 2018). "Autosomal dominant polycystic kidney disease (ADPKD) is an adult-onset disease characterized by focal cyst development resulting from heterozygous mutations in PKD1 or PKD2." (PMID 29443690, 2018). "The significance of synonymous variants in PKD1, one of the genes underlying autosomal dominant polycystic kidney disease, has recently been described." (PMID 30002499, 2018). "A similar inheritance pattern explained some rare severe and early onset cases of autosomal dominant polycystic kidney disease when hypomorphic PKD1 mutations were co-inherited with variants in the PKHD1 or the HNF-1β gene." (PMID 28334007, 2017). "Autosomal dominant polycystic kidney disease (ADPKD) is caused by mutations in PKD1 or PKD2 which encodes polycystin-1 (PC1) and polycystin-2, respectively." (PMID 28904368, 2017). "Autosomal dominant polycystic kidney disease was originally thought to be caused by mutations in two genes; PKD1 (on chromosome 16p13.3) (OMIM #173900) and PKD2 (on chromosome 4q21) (OMIM #173910)." (PMID 28473970, 2017). "In humans, autosomal dominant polycystic kidney disease (ADPKD) is associated with loss-of-function mutations in genes that encode for either PKD1 or PKD2." (PMID 27348301, 2016). "Herein we report a novel mutation in PKD1 gene, which results in autosomal dominant polycystic kidney disease (APKD), one of the commonest severe renal disorders." (PMID 27478809, 2016). "Autosomal Dominant Polycystic Kidney Disease (ADPKD) arises from mutations to either polycystin 1 or 2 (PC1 or PC2, gene name Pkd1 and Pkd2)." (PMID 27081851, 2016). "Mutations in TSC1 or TSC2 cause the tuberous sclerosis complex (TSC), while mutations in PKD1 or PKD2 cause autosomal dominant polycystic kidney disease (ADPKD)." (PMID 26077033, 2015). "Autosomal-dominant polycystic kidney disease arises from inactivating mutations in the genes PKD1 or PKD2, and currently has few treatment options." (PMID 26528438, 2015). "Systemic manifestations of OFD1 mutations include polycystic kidneys that resemble those caused by mutations in the PKD1 or PKD2 genes associated with autosomal dominant polycystic kidney disease (ADPKD)." (PMID 25180832, 2014). "Typically, the functions of PC1 and PC2 are interdependent and concordant, as evidenced by common Autosomal Dominant Polycystic Kidney Disease (ADPKD) phenotype caused by inactivation of either PKD1 or PKD2." (PMID 25464512, 2014). "About 2% to 3% of patients carrying a TSC2 mutant gene will also have a grave form of autosomal dominant polycystic kidney disease caused by a deletion in a segment of the pkd1 and TSC2 genes known as contiguous gene syndrome." (PMID 23401839, 2013). "Autosomal dominant polycystic kidney disease is an inherited disorder most often caused by mutations in the PKD1, which encodes the polycystin-1 protein." (PMID 24379984, 2013). "Polycystin-1 is a large, plasma membrane receptor encoded by the PKD1 gene, which is mutated in autosomal-dominant polycystic kidney disease (ADPKD)." (PMID 22974282, 2012). "Studies in humans have shown that 85–90% of Autosomal Dominant Polycystic Kidney Disease (ADPKD) (OMIM ID: 173900) is caused by mutations in PKD1 (Entrez Gene ID: 5310), with other cases caused by mutations in PKD2 (Entrez Gene ID: 5311)." (PMID 21818326, 2011). "Further, Autosomal Dominant Polycystic Kidney Disease in Persian cats (OMIA ID: 1451) is caused by a premature truncating mutation in the feline Pkd1 orthologue (Entrez Gene ID: 100144606)." (PMID 21818326, 2011).